SMAD7 (SMAD family member 7)
Diseases named in the same sentence as SMAD7 in open-access papers (continued):
Sharing a sentence is not in itself a finding about the gene and the disease.
colon carcinoma (32 papers, 2008 to 2025). "In colon cancer, SMAD7 deletion predisposes to a favorable prognosis, while SMAD7 amplification is linked to poor outcomes." (PMID 36578789, 2022). "The overexpression of SMAD7 is associated with the development of skin, pancreatic, lung, and colon cancer in the processes of cell growth and apoptosis." (PMID 33413425, 2021). "In colon cancer, SMAD7 deletion predisposes to a favorable prognosis compared to patients with two copies of the gene, whereas patients with SMAD7 gene amplification exhibit significantly worse outcomes." (PMID 29799477, 2018). "SMAD7 has been implicated in colon cancer development, and in interactions with β-catenin in pancreatic cancer and prostate cancer." (PMID 28118365, 2017). "The purpose of this study is to understand the stage-specific duality of TGF-β and Smad function, and the molecular mechanism underlying the role of Smad7 in the metastasis of colon cancer." (PMID 18781153, 2008). "SMAD7 showed only weak evidence of association with colon cancer (P = 0.058)." (PMID 29986644, 2018). "High levels of either VEGF-D or SMAD7 can serve as predictors of poor prognosis and chemotherapeutic outcome in colon cancer." (PMID 34198654, 2021). "Stable expression of Smad7 in colon cancer induces liver metastasis by negatively regulating the TGF-β/Smad pathway." (PMID 34059951, 2021). "In colon cancer transplantation experiments, the development of tumors in T cell-specific Smad7 transgenic mice was inhibited relative to that in wild-type (WT) mice, with the resistance dependent on CD4+ T cells." (PMID 34059951, 2021). "Blocking the TGF-β/Smad pathway while stably expressing Smad7 in colon cancer cells induced liver metastasis, indicating that the Smad signaling pathway plays an important role in inhibiting the metastasis of colon cancer." (PMID 34059951, 2021). "We here review the available evidence supporting the involvement of Smad7 in intestinal inflammation and colon cancer (CC)." (PMID 33920230, 2021). "The SMAD7, SMAD3, BMP2, and C-MYC regions were associated with colon cancer; however, after BH correction, only SMAD7 (PBH = 0.04) and SMAD3 (PBH = 0.009) remained statistically significant." (PMID 31434255, 2019). "Smad7 expression is also upregulated in colon cancer cells, in which such a protein controls positively intracellular pathways that sustain neoplastic cell growth and survival." (PMID 29973939, 2018). "Further, miR-25 is downregulated in colon cancer and putatively targets Smad7 as a tumor suppressor." (PMID 29152124, 2017). "On the other hand, downregulated miR-25 was found in human colon cancer tissues, in which it inhibited cell proliferation and migration in cell lines and suppressed the growth of colon cancer cell xenografts by targeting Smad7 in colon cancer." (PMID 28466015, 2017). "In colon cancer cells, stable expression of SMAD7 blocks the TGF-β-mediated activation of NFκB, a critical molecule in oxidative-stress-induced apoptosis." (PMID 23560096, 2013). "The same group assessed the role of Smad7 in colon cancer metastasis and demonstrated that injection of Smad7-overexpressing FET cells in the spleen of athymic nude mice favored the development of liver metastasis." (PMID 24317436, 2013). "Interestingly, the stratified analyses revealed that the rs4939827 (18q21.1) variant's association was limited to women only (OR = 0.6, 95% CI 0.42–0.88, p = 0.007), indicating that common genetic variants in SMAD7 may confer susceptibility to colon cancer particularly among women." (PMID 22532847, 2012). "We demonstrated previously that Smad7 induces tumorigenicity in colon tumour-derived FET cells by blocking TGF-β-induced growth inhibition and apoptosis." (PMID 18781153, 2008). "In an experimental model of colon cancer liver metastasis, we have shown that the stable expression of Smad7 enhances liver metastasis." (PMID 18781153, 2008).
colon carcinoma (continued). "Smad7 has been reported to act as a pro-carcinogenic factor by sustaining colon cancer survival." (PMID 28881698, 2017). "These apparently contradictory results regarding the role of Smad pathway in metastasis prompted us to test whether inhibition of Smad pathway by Smad7 induces invasion and metastasis of colon cancer cells." (PMID 18781153, 2008). "They found that carriers of risk alleles at loci rs4939827 of SMAD7 gene could harbor increased susceptibility to development of rectal cancer rather than colon cancer." (PMID 32190221, 2020). "Lymphatic vasculature—Little information is available on the functions of I-SMADs in the lymphatic vasculature, yet SMAD7, SMAD4 and VEGF-D have been correlated with lymphangiogenesis and lymph node metastasis in patients with colon cancer." (PMID 34198654, 2021). "Therefore, it might function as a tumor suppressor by targeting Smad7 in colon cancer." (PMID 25126546, 2014). "Notably, TMEM220-AS1, TMEM238L, SOX6, SMAD7, TCF7L2, and PYGL were significantly downregulated in colon cancer, whereas LINC02257, PCAT1, CASC8, and POU5F1B were significantly upregulated in colon cancer." (PMID 41144378, 2025). "However, we failed to observe significant alterations in Smad7 expression and Smad2/3 phosphorylation upon overexpression or suppression of Nur77 in colon cancer cells, suggesting a distinct mode of Nur77 action in colon cancers." (PMID 33990575, 2021). "Here, we review and discuss the available evidence about the role of TGF-β1 and Smad7, an inhibitor of TGF-β1 activity, in gut inflammation, fibrosis and cancer with particular regard to the contribution of these two molecules in the pathogenesis of inflammatory bowel diseases and colon cancer." (PMID 33375423, 2020). "Interestingly, we observed a reduced level of Smad7 in colon cancer cells following NRP2 gene transfer (data not shown)." (PMID 21747928, 2011).
pancreatic cancer (32 papers, 2007 to 2026). "In pancreatic cancer, elevated expression of Smad7 associates with a better prognosis as compared to patients with lower expression, who show higher incidence of lymph node and liver metastasis after surgery." (PMID 31052449, 2019). "Low expression of Smad7 was associated with enhanced metastasis and poor prognosis in pancreatic cancer." (PMID 27006642, 2016). "More recently, Kuang and co-workers provided in vivo evidence that Smad7 is implicated in the early stages of pancreatic cancer." (PMID 24317436, 2013). "Studies investigating the mechanisms underlying the pro-tumorigenic effects of Smad7 identified thioredoxin-1 and retinoblastoma as key molecules involved in the Smad7-dependent aggressiveness of pancreatic cancer cells." (PMID 24317436, 2013). "However, Wang and co-workers showed that high expression of Smad7 in pancreatic cancer associated with a more favorable prognosis compared with patients with lower levels of Smad7 who exhibited increased incidence of lymph node metastasis and liver metastasis after surgery." (PMID 24317436, 2013). "Immunofluorescence staining confirmed the colocalization of VASP and SMAD7 in pancreatic cancer cells." (PMID 41285728, 2025). "In conclusion, we found that the EMP1-promoted binding of VASP and SMAD7 in pancreatic cancer promotes the activation of the TGF-β/Smads signaling pathway characterized by enhanced phosphorylation of SMAD2/3." (PMID 41285728, 2025). "SMAD7 is a direct target of miR-367 in human pancreatic cancer cells and it promotes the invasion and metastasis of pancreatic cancer cells through the TGF-β signaling pathway." (PMID 37510338, 2023). "Zhou reported that overexpression of SMAD7 promoted proliferative and migratory capacities in pancreatic cancer." (PMID 35912252, 2022). "miRNA-367 promotes the invasiveness and metastasis of human pancreatic cancer cells by directly targeting the 3-untranslated region (3-UTR) of SMAD7, downregulating its expression of Smad7, and enhancing the TGF-β/Smad signaling pathway." (PMID 34059951, 2021). "Increased levels of SMAD7 were observed in approximately 50% of pancreatic cancer cases, with increased SMAD7 and YAP1 mRNA expression found to contribute to resistance against TGF-β signaling in this condition." (PMID 33763375, 2021). "The pancreatic cancer cells transfected with SMAD7 have been found to have increased malignancy and enhanced tumorigenic ability in nude mice, suggesting that abnormal expression of SMAD7 will contribute to tumor development." (PMID 34254453, 2021). "The study also reported that miR-487a-3p target SMAD7, which is the downstream signal conveyed in pancreatic cancer." (PMID 33724144, 2021). "Jungert revealed that Smad proteins and SP1 cooperatively regulate expression of a distinct set of TGF‐β target genes potentially involved in tumour progression, including MMP‐11, cyclin D1 and Smad7 in pancreatic cancer cells." (PMID 32729205, 2020). "A previous study reported that low levels of Smad7 expression in pancreatic cancer are closely related to lymph node metastasis and poor prognosis." (PMID 33255941, 2020). "Related studies showed that miR-367 promoted pancreatic cancer invasion in vitro and metastasis in vivo through downregulating Smad7." (PMID 26552593, 2015). "Studies have also found upregulation of Smad7 mRNA in pancreatic cancer as compared to normal tissue." (PMID 24047375, 2013). "An early study by Kleeff and colleagues showed that Smad7 RNA transcripts were increased in human pancreatic cancer as compared to the normal pancreas." (PMID 24317436, 2013). "One of them conducted in pancreatic cancer cell line, found Smad6 and Smad7 levels to be elevated in pancreatic cancer." (PMID 22195733, 2011).
pancreatic cancer (continued). "In fact, different studies have isolated different molecules, like KLF11, retinoblastoma, thioredoxin, which are involved in Smad7 dependent aggressiveness of pancreatic cancer." (PMID 22195733, 2011). "Over-expression of inhibitory Smad6 and Smad7 was described in pancreatic cancer and in pancreatic cancer cell lines." (PMID 20462450, 2010). "A pancreatic cancer cell line engineered to overexpress Smad7 are resistant to the actions of TGF-β1 with respect to growth inhibition and cisplatin-induced apoptosis." (PMID 19081766, 2008). "A previous study demonstrated that Smad3 and Smad7 expression exhibits circadian rhythms in pancreatic cancer cells and zebrafish, suggesting that their expression may be regulated by intrinsic circadian clock mechanisms." (PMID 41257391, 2026). "Aberrant SMAD7 expression contributes to the invasion and metastasis of pancreatic cancer cells." (PMID 32545415, 2020). "However, a low level of miR-487a-3p is linked to a high metastasis rate and poor prognosis by targeting SMAD7 in pancreatic cancer tissues." (PMID 33520987, 2020). "Additionally, Trx is downstream of Smad7 in a pathway that confers a growth advantage to pancreatic cancer cells and that increases their resistance to cisplatin-mediated apoptosis." (PMID 31470801, 2019). "SMAD7 might be a target for inhibition of IL-1α-dependent stimulation of pancreatic cancer cell migration." (PMID 27473228, 2016). "The reason for this apparent difference is not yet known even though it is conceivable that such a discrepancy could be at least in part due to the ability of Smad7 to interfere with the opposing role of TGF-β in pancreatic tumor initiation and progression." (PMID 24317436, 2013). "Others have shown that SMAD6 and SMAD7 are upregulated in pancreatic cancer." (PMID 23049692, 2012). "Moreover, a key role of Sp1 in the Smad7 induction by TGFβ was recently established in pancreatic cancer cells." (PMID 21324108, 2011). "Previous studies have shown Smad7 overexpression in pancreatic cancer cell lines." (PMID 22195733, 2011). "We also identified different roles for Smad6 and Smad7 in influencing pancreatic cancer biology." (PMID 22195733, 2011). "Interestingly, thioredoxin is identified as a gene whose basal expression is increased in pancreatic cancer cells in which Smad7 is commonly overexpressed." (PMID 17224927, 2007). "However, some in vivo and in vitro studies support the hypothesis that Smad7 exerts a pro-tumorigenic effect in pancreatic cancer cells." (PMID 31052449, 2019). "In addition, SMAD7 mRNA levels are increased in human pancreatic cancer." (PMID 25295107, 2014). "Besides, Co-IP analysis illustrated that in pancreatic cancer cells, SMAD7 could bind to the VASP protein, and after knockdown of EMP1 protein in pancreatic cancer cells, the ability of VASP protein binding to SMAD7 was inhibited, and the reverse result was obtained by overexpression of EMP1." (PMID 41285728, 2025). "Among the five TFs identified, activation of SMAD3 and inhibition of SMAD7 may together indicate a possible activation of TGF-beta signaling, which is known to play a dual role as both pro-tumorigenic and tumor-suppressive in pancreatic cancer, depending on tumor stage and microenvironment." (PMID 33194391, 2020). "SMAD7-silenced PSCs were incubated in the presence or absence of IL-1α, and the effect of PSC-conditioned medium was assessed in a wound closure model using BxPC-3 pancreatic carcinoma cells." (PMID 27473228, 2016).
colitis (31 papers, 2011 to 2023). Inflammation of the colon. "Consistently, Smad7-deficient DCs promoted the differentiation of naive CD4+ T cells into Foxp3+ Tregs, and mice with Smad7-deficient DCs developed less severe DSS-induced colitis compared to controls." (PMID 36714553, 2023). "To further explore the role of T cell-associated Smad7 on ongoing colitis, we generated a transgenic (Tg) mouse over-expressing Smad7 selectively in T cells and NKT cells." (PMID 36714553, 2023). "Conversely, the opposing role of SMAD7 in the control of sporadic and colitis-associated CRC has been shown by one study; they reported that over-expression of SMAD7 in T cells is associated with severe colitis and reduces the growth of colitis-associated CRC." (PMID 32190221, 2020). "Smad7 Tg mice were largely protected from tumors compared to sham, thus highlighting the opposing role of Smad7 in the control of sporadic and colitis-associated CRC." (PMID 33375423, 2020). "In this review, we summarize the available evidences about the role of Smad7 in both sporadic and colitis-associated CRC." (PMID 31052449, 2019). "Next, we developed transgenic mice over-expressing Smad7 in T cells and assessed the susceptibility of such animals to develop colitis following oral administration of dextran sodium sulfate (DSS) and DSS-driven CAC." (PMID 31052449, 2019). "Induction of DSS-colitis associates with significant reduction of Sirt1 in both WT and Smad7 Tg mice, but this effect is more prominent in Smad7 Tg mice." (PMID 30147698, 2018). "In both these models, the elevated levels of Smad7 associate with reduced Smad3 phosphorylation, and colitic mice given oral Smad7 AS show enhanced phosphorylation of Smad3, reduced synthesis of inflammatory cytokines and amelioration of colitis." (PMID 33920230, 2021). "In addition, AOM‐DSS‐treated mice with ectopic Smad7 expression in T cells showed more severe colitis but reduced tumor load, which was associated with increased tumor immune surveillance by CD8+ T cells." (PMID 29419930, 2018). "Interestingly, a study demonstrated that while Smad7 overexpression in T cells increases colitis severity, it decreases colitis-associated cancer." (PMID 25566830, 2015). "Conversely, the opposing role of SMAD7 in the control of sporadic and colitis-associated CRC has been shown by one study in which they reported that over-expression of SMAD7 in T cells associates with severe colitis and reduces the growth of colitis-associated CRC." (PMID 25289133, 2014). "More recently, it was found that overexpression of Smad7 in T cells was able to suppress colitis-associated tumors in the mice, accompanied by elevated expression of interferon-γ (IFNγ) and accumulation of cytotoxic CD8+ and Natural Killer (NK) T cells in the tumors and peritumoral areas." (PMID 22204639, 2011). "Moreover, treatment of those mice with blocking antibodies to either PD1 or CD25 abrogated colitis resistance observed in mice with Smad7-deficient DCs, supporting the contribution of Tregs and Treg-promoting PD1 signaling in mitigating colitis severity in mice carrying on Smad7-deficient DCs." (PMID 36714553, 2023). "In line with this is the observation that Smad7 levels are up-regulated in patients with CMV-induced colitis and its expression declines after antiviral treatment." (PMID 36714553, 2023). "PDL1/2+DCs are more developed when they are SMAD7 deficient, such cells induce CD4+ T cell‐to‐Treg differentiation and reduce the severity of colitis in mice." (PMID 36625080, 2023). "Consistently, knockdown of Smad7 restores TGF-β1 function thereby attenuating intestinal inflammation in patients with IBD as well as in mice with IBD-like colitis." (PMID 36714553, 2023). "During the acute phases of human IBD and experimental colitis in mice, Smad7 is over-expressed by mucosal T cells." (PMID 36714553, 2023).